CDK7 (cyclin dependent kinase 7)
Diseases named in the same sentence as CDK7 in open-access papers (continued):
Sharing a sentence is not in itself a finding about the gene and the disease.
glioma (11 papers, 2017 to 2025). A benign or malignant brain and spinal cord tumor that arises from glial cells (astrocytes, oligodendrocytes, ependymal cells). "In addition, we found that glioma cells are extremely susceptible to the inhibitor of CDK7, as this inhibition represses SE-driven-LIMD1-AS1." (PMID 37385987, 2023). "Nevertheless, some studies suggest that CDK7 maintains glioma stemness and confers apoptosis resistance in A172 cells by activating pro-survival pathways such as STAT3 and Notch." (PMID 40843352, 2025). "Most importantly, CDK7 significantly correlated with MED1 expression in glioma tissues from the TCGA and CGGA database." (PMID 37385987, 2023). "Our findings support the idea that CDK7 mediated-epigenetically activation of LIMD1-AS1 plays a crucial role in glioma progression and provides a promising therapeutic approach for patients with glioma." (PMID 37385987, 2023). "THZ1, a covalent inhibitor of CDK7, has shown promising therapeutic effects in preclinical models for a range of malignancies, including high-grade glioma, hepatocellular carcinoma, and non-small cell lung cancer." (PMID 35945614, 2022). "CDK7 inhibition has previously been reported to downregulate EGFR in high-grade glioma and PLK2 in a lung cancer cell line." (PMID 32155786, 2020). "Together, these data indicated that MED1 might be involved in the function of CDK7 as an epigenetic activator of LIMD1-AS1 in glioma cells." (PMID 37385987, 2023). "Our findings provide further evidence that a covalent CDK7 inhibitor may benefit glioma patients with high expression of LIMD1-AS1." (PMID 37385987, 2023). "For example, high CDK7 expression is associated with favorable prognosis in adrenocortical carcinoma (ACC) and high CDK9 expression with favorable prognosis in pancreatic adenocarcinoma (PAAD) and low-grade glioma (LGG)." (PMID 36577800, 2022). "However, it is necessary to observe whether a hypersensitive subset can be identified through phospho-MED1 levels in glioma hypersensitive to CDK7 inhibition." (PMID 37385987, 2023). "Experimental evidence suggests that inhibiting CDK7 significantly mitigates the recruitment of MED1 to super-enhancers, providing a promising strategy for glioma treatment." (PMID 38967893, 2024). "Activation of CDK7 significantly enhances the recruitment of MED1 to the super-enhancer of LIMD1-AS1, thereby enhancing the expression of LIMD1-AS1 and promoting glioma cell proliferation." (PMID 38967893, 2024). "Firstly, the inhibition of CDK7 decreased the mRNA expression of MED1 in LN-18 and T98G glioma cells." (PMID 37385987, 2023). "THZ1, a CDK7 inhibitor, treatment markedly reduced LIMD1-AS1 expression in LN-18 and T98G glioma cells." (PMID 37385987, 2023). "Our results confirmed that inhibition of CDK7 attenuates MED1 recruitment to the super-enhancer of LIMD1-AS1 and then decreases the expression of LIMD1-AS1 in glioma cells." (PMID 37385987, 2023). "To address the translational potential of LIMD1-AS1, we prioritized A covalent CDK7 Inhibitor, THZ1, for further investigation based on the expression of LIMD1-AS1 in glioma." (PMID 37385987, 2023). "We examined the subcellular location of CDK7 and MED1 using immunofluorescence staining and found that CDK7 mainly colocalized with MED1 in the nucleus of LN-18 and T98G glioma cells." (PMID 37385987, 2023). "Furthermore, endogenous CDK7 coimmunoprecipitated with endogenous MED1 in LN-18 and T98G glioma cells." (PMID 37385987, 2023). "To further verify whether MED1 is involved in epigenetic activation of LIMD1-AS1 induced CDK7, we observed LIMD1-AS1 expression after co-transfection of si-MED1 and CDK7 to SF126 glioma cells." (PMID 37385987, 2023). "Similarly, CDK7 knockdown also markedly decreased LIMD1-AS1 expression in LN-18 and T98G glioma cells." (PMID 37385987, 2023).
glioma (continued). "In summary, our results provide novel evidence that epigenetic modifications of LIMD1-AS1 are mediated by CDK7-activated interferon pathways by directly binding HSPA5, which might contribute to glioma progression." (PMID 37385987, 2023). "We found that the inhibition of CDK7 decreased the binding of MED1 across the LIMD1-AS1 super-enhancer, but not the promoter, in LN-18 and T98G glioma cells." (PMID 37385987, 2023). "In addition to inhibiting CDK7, SNS-032 also inhibits the cyclin-dependent kinases CDK2, CDK5 and CDK9, however, even though SNS-032 can alter glioma response to hypoxia, it is not toxic toward U87 cells even at very high drug concentrations (500 nM)." (PMID 29844863, 2018).
lung carcinoma (11 papers, 2015 to 2025). "CDK7 inhibition has been reported to reduce abnormal cell proliferation associated with lung cancer." (PMID 37476070, 2023). "Yang used gene chip technology to screen the differentially expressed genes in cisplatin-resistant lung adenocarcinoma cells and found that CDK7 was highly expressed, suggesting that CDK7 is associated with cisplatin resistance in lung carcinomas." (PMID 25411854, 2015). "It has been demonstrated that CDK7 inhibition disrupted cell‐cycle progression and induces DNA replication stress and genome instability in lung cancer while triggering immune‐response signaling." (PMID 37476070, 2023). "Inhibition of CDK7/12 promotes resistance emergence in response to targeted therapy in lung cancer cells." (PMID 37519889, 2023). "CDK7 inhibitors induce cell cycle arrest and apoptosis of lung cancer cells via blocking the glucose consumption or interfering with cancer metabolism." (PMID 33889549, 2021). "A recent study identified that CDK7 is a key regulator of glucose consumption, and CDK7 inhibitors block glucose consumption in lung cancer cells." (PMID 33889549, 2021). "Notably, CDK7 inhibition has been shown to boost anti–PD-1 responses in lung cancer models, suggesting a possible parallel worth exploring in GBM." (PMID 40996961, 2025). "In addition, it has been reported that the high expression of CDK7 is positively correlated with poor survival rate in lung cancer." (PMID 37476070, 2023). "There are only few studies dealing with protein expression of CDK7 on lung cancer." (PMID 36212402, 2022). "BRD4 and CDK7 are key factors for the function of epigenetic elements such as enhancers, and their inhibitors, JQ1 and THZ1, globally inhibit the expression of associated genes and suppressed lung cancer cell proliferation." (PMID 34001209, 2021). "RNA interference technology was used to specifically silence CDK7 and observe the effect of CDK7 downregulation on the biological characteristics of cisplatin-resistant A549/CDDP human lung carcinoma cells." (PMID 25411854, 2015). "The CDK7 and PLK1 inhibitors played a critical role in immunotherapies for lung cancer." (PMID 34721732, 2021). "The role of CDK7 in NSCLC has not yet been investigated as thoroughly as in other malignancies, and concerning lung cancer, there are already more insights for SCLC than for NSCLC." (PMID 36212402, 2022).
non-small cell lung carcinoma (11 papers, 2020 to 2025). A group of at least three distinct histological types of lung cancer, including non-small cell squamous cell carcinoma, adenocarcinoma, and large cell carcinoma. "CDK7 inhibitors can improve the efficacy of anti-PD-1 therapy for non-small cell lung cancer (NSCLC).Therefore, we further investigated the relationship between CDC25B and the TME and immune checkpoints." (PMID 39371450, 2024). "The CDK7 inhibitor THZ1 in combination with ICI showed promising results in treatment for non-small cell lung cancer." (PMID 36497420, 2022). "The CDK7 is highly expressed in non-small cell lung cancer, silencing and inhibiting CDK7-inhibited tumor growth." (PMID 36287961, 2022). "Previous study reported that CDK7 inhibition suppresses human non-small-cell lung cancer cells through interference with cancer metabolism." (PMID 33889549, 2021). "Here, we investigated whether EMT is associated with acquired resistance to 3rd generation EGFR-TKIs, and we explored the effects of cyclin-dependent kinase 7 (CDK7) inhibitors on EMT-mediated EGFR-TKIs resistance in non-small cell lung cancer (NSCLC)." (PMID 33287368, 2020). "Through this and validation with various assays, they identified that Cyclin-dependent kinase 7 (CDK7) is a driver of glucose consumption and inhibition with the CDK7 inhibitor, Milciclib, decreased glucose metabolism in non-small-cell lung cancer cells." (PMID 40943388, 2025).
gastric cancer (10 papers, 2009 to 2025). A primary or metastatic malignant neoplasm involving the stomach. "Therefore, CDK7 has been implicated as a therapeutic target for gastric cancer." (PMID 36769170, 2023). "In gastric carcinoma, high CDK7 protein expression significantly predicted an unfavourable prognosis." (PMID 38037549, 2023). "Up-regulation of CDK7 in gastric cancer cells has been shown to promote tumor cell proliferation and predicts poor prognosis." (PMID 28938550, 2017). "Inhibition of CDK7 by gambogic acid induced irreversible arrest of G2/M phase in gastric cancer cells, and is thus a putative treatment target." (PMID 19662092, 2009). "Moreover, the CDK7-specific inhibitor BS-181 has also shown promising results against gastric cancer cells, leading to reduced invasion, migration, and proliferation in the gastric cancer cell line." (PMID 36769170, 2023). "CDK7 expression levels have been correlated with matrix metalloproteinase 14 (MMP14) in gastric cancer, and higher expression of these proteins, along with the mRNA of their genes, has been associated with lymph node matastasis of gastric cancer and worse prognosis of the disease." (PMID 36769170, 2023). "CDK7 inhibition using a specific inhibitor named THZ2 results in the generation of ROS, induction of cell cycle arrest, and apoptosis in gastric cancer cells in in vitro and in vivo conditions." (PMID 36769170, 2023).
hepatocellular carcinoma (10 papers, 2013 to 2024). A malignant tumor that arises from hepatocytes. "In a previous study on hepatocellular carcinoma, we reported that transcription inhibition via a CDK7 inhibitor targeting RNA polymerase II drastically decreased MYC cellular level." (PMID 37898690, 2023). "THZ1, as a CDK7 covalent inhibitor, is effective in several types of cancers, including esophageal squamous cell carcinoma, hepatocellular carcinoma, and so on." (PMID 31399555, 2019). "CDK7 has been found to activate the β-catenin pathway in hepatocellular carcinoma." (PMID 38540292, 2024). "Ibulocydine (IB) is a novel CDK7/9 inhibitor prodrug with an isobutyrate ester structure that has anti-cancer effects against human hepatocellular carcinoma (HCC) cells compared to normal liver cells." (PMID 38892310, 2024). "Xylocydine is a novel cyclin-dependent kinase (cdk) inhibitor that induces apoptosis in hepatocellular carcinoma (HCC) cells by inhibiting Cdk1, Cdk2, Cdk7, and Cdk9 activities." (PMID 23344045, 2013). "The results showed that knocking down either HNF4α or Exo70 in human hepatoma cells reduced the expression of Cdc2, while had no influence on the expression of Cyclin B1 and Cdk7." (PMID 26848864, 2016).
pancreatic cancer (10 papers, 2019 to 2023). "Data from TCGA-PDAC indicated that increased CDK7 expression is statistically associated with poor overall survival in PDAC, and CDK7 is upregulated in pancreatic cancer compared to normal tissues." (PMID 35945614, 2022). "Multivariable‐adjusted associations of CDK7 expression with overall survival (OS) and disease‐free survival (DFS) after excluding cases who died within 3 months after resection in our resected pancreatic cancer cohort, stratified by KRAS." (PMID 38037549, 2023). "Our investigations of a panel of human pancreatic tumor cells now reason for a broad role of CDK7 in maintaining expression of genes involved in control and execution of the cell cycle program." (PMID 35054996, 2022). "Specific focus was on two representative cell lines, Mia-Paca2 and Panc89, originating from different stages and tissues of human pancreatic tumors and reacting to CDK7 inhibition with distinct sensitivity." (PMID 35054996, 2022). "We demonstrated here that CDK7 is a novel therapeutic target for pancreatic cancer, which relies on its promotion of cell cycle progression, as well as its interference with DNA damage/DNA damage repair and apoptosis induction." (PMID 35945614, 2022). "A rising number of studies have recently focused on the role of CDK7 in cancer, but we observed limited data on the role of CDK7 inhibitors in combination with chemotherapy, particularly in pancreatic cancer." (PMID 35945614, 2022). "Already the selected protein analysis lends support to the hypothesis of a more general role of cell cycle gene expression control by CDK7 in pancreatic cancer." (PMID 35054996, 2022). "Here, we used a sgRNA library focused on kinases and PDAC-associated genes and identified CDK7 as a candidate for chemotherapy sensitization in pancreatic cancer by adopting a systematic approach of negative selection of CRISPR-Cas9." (PMID 35945614, 2022). "In this study, the authors identified an ITK inhibitor, NCGC00188382, which could inhibit the activity of TAOK3, aurora B kinase, and cyclin-dependent kinase 7 in cancer cells and suppress the stemness traits and growth of pancreatic tumors." (PMID 33050415, 2020). "In addition, a previously identified ITK inhibitor (NCGC00188382) was shown to inhibit the activity of TAOK3, aurora B kinase, and cyclin-dependent kinase 7 in pancreatic cancer cells and suppress the stemness traits and growth of tumor spheroids." (PMID 33050415, 2020). "Interestingly, our data suggest that TPL elicits a similar transcriptional change to that of CDK7 inhibition by THZ1 or THZ2 in pancreatic cancer cells." (PMID 33168807, 2020). "Here, we employed a previously developed, highly specific small molecule inhibitor that non-covalently blocks ATP binding to CDK7 (LDC4297) to study the mechanisms underlying cell line-specific growth using a panel of genetically heterogeneous human pancreatic tumor lines as model system." (PMID 35054996, 2022). "A representative panel of nine human pancreatic cancer cell lines was chosen to investigate the effects of non-covalent CDK7 inhibition by LDC4297." (PMID 35054996, 2022). "We then conducted cell viability, clonogenic, and apoptosis assays and evaluated the synergistic therapeutic effects of cyclin-dependent kinase 7 (CDK7) depletion or inhibition with gemcitabine (GEM) and paclitaxel (PTX) in a murine orthotopic pancreatic cancer model." (PMID 35945614, 2022).
esophageal squamous cell carcinoma (8 papers, 2017 to 2026). Esophageal squamous cell carcinoma (ESCC) is a type of esophageal carcinoma (EC) that can affect any part of the esophagus, but is usually located in the upper or middle third. "who examined protein expression of CDK7 in 98 esophageal squamous cell carcinomas (ESCC) used the same score and with that found a higher proportion of CDK7 high expressing tumors (81.6%, n=80)." (PMID 36212402, 2022). "Meanwhile, in esophageal squamous cell carcinoma (ESCC), the CDK7-YAP-LDHD axis helps ESCC-CSCs evade D-lactate-induced ferroptosis and generates pyruvate to meet their energy needs for self-renewal." (PMID 41601687, 2026). "CDK7-YAP-LDHD crosstalk enhances D-lactate elimination and ferroptosis resistance to sustain tumor stem cell-like capacities in esophageal squamous cell carcinoma (ESCC)." (PMID 39709438, 2024).
colorectal cancer (7 papers, 2015 to 2024). A primary or metastatic malignant neoplasm that affects the colon or rectum. "Syros Pharmaceuticals recently announced it will begin investigating the CDK7 inhibitor SY-5609 in combination with atezolizumab in patients with BRAF-mutant colorectal cancer." (PMID 35568739, 2022). "CDK7 was highly expressed in some colorectal cancer tissues but downregulated in others." (PMID 35814446, 2022). "In summary, as a prospective inhibitor of CDK7, THZ2 can alleviate the inflammatory symptoms, both in DSS-induced acute colitis and AOM/DSS-induced colorectal cancer mouse models, inhibiting colitis and tumor cell proliferation." (PMID 38540292, 2024). "Our study found that THZ2 may exert its inhibitory effect on colorectal cancer development by reducing the expression of β-catenin and snail in AOM/DSS mouse models, suggesting that CDK7 could potentially serve as a therapeutic target in cancer treatment by affecting β-catenin." (PMID 38540292, 2024).
osteosarcoma (7 papers, 2021 to 2025). A usually aggressive malignant bone-forming mesenchymal neoplasm, predominantly affecting adolescents and young adults. "The covalent CDK7 inhibitor THZ2 demonstrated significant suppression of osteosarcoma tumor growth and metastasis by targeting super-enhancer-associated oncogenes." (PMID 37197432, 2023). "In conjunction, BRD4 and CDK7 based drugs targeting critical components of SEs have been developed to treat osteosarcoma, Ewing sarcoma, multiple myeloma, osteoarthritis, and other bone-related diseases." (PMID 35663324, 2022). "CDK7 upregulation was revealed in 35 osteosarcoma primary tumours compared to normal tissue." (PMID 38542080, 2024). "Inhibition of CDK7 suppressed the metastasis of osteosarcoma." (PMID 33686962, 2021). "Prior studies show efficacy of statins, BET/CDK7 inhibitors, and SOAT1 blockade (e.g., avasimibe) in osteosarcoma or related cancer models, with SREBP-axis inhibitors (e.g., fatostatin) providing complementary upstream control." (PMID 41358198, 2025). "All 10 examined osteosarcoma cell lines have shown high sensitivity to THZ2, a selective CDK7 inhibitor." (PMID 38542080, 2024). "documented that blocking SEs by CDK7 inhibitor THZ2 suppresses the growth and metastasis in osteosarcoma." (PMID 36254394, 2022).
acute myeloid leukemia (6 papers, 2021 to 2023). Acute myeloid leukemia (AML) is a group of neoplasms arising from precursor cells committed to the myeloid cell-line differentiation. "SY-1365 (a THZ1 derivative), a selective inhibitor of CDK7 under clinical trials in breast and ovarian cancers, preferentially decreased the expression of SE-related oncogenic genes with very little influence on housekeeping genes in acute myeloid leukemia (AML) cells." (PMID 35277481, 2022).
pancreatic ductal adenocarcinoma (5 papers, 2020 to 2025). An infiltrating adenocarcinoma that arises from the epithelial cells of the pancreas. "JQ1 in combination with cyclin-dependent kinase 7 (CDK7) inhibitor THZ1 loaded in polyester NPs was reported as an effective molecular therapeutic option for the treatment of pancreatic ductal adenocarcinoma (PDAC)." (PMID 36139634, 2022). "Compared to free drugs, the codelivery of JQ1 and the cyclin-dependent kinase 7 inhibitor THZ1 significantly enhanced tumour-inhibition effects in a gemcitabine-resistant pancreatic ductal adenocarcinoma patient-derived xenograft model." (PMID 36139634, 2022). "Inhibition of CDK7, a potent transcription regulator, may bring new hope for treating pancreatic ductal adenocarcinoma (PDAC), which is featured by large genetic heterogeneity and abundant KRAS mutations." (PMID 38037549, 2023).